SSX2 (SSX family member 2)
Diseases named in the same sentence as SSX2 in open-access papers (continued):
Sharing a sentence is not in itself a finding about the gene and the disease.
tumor (51 papers, 1999 to 2026). "We have previously demonstrated that a DNA vaccine encoding SSX2 can mediate anti-tumor responses in tumor-bearing mice." (PMID 27661128, 2016). "Due to SSX2's association with focal adhesion and cell migration, we next investigated the effects of SSX2 knockdown on tumor growth in vivo." (PMID 27276714, 2016). "In particular, antigens belonging to the Melanoma Antigen Gene family (MAGE-A1, MAGE-A3, MAGE-A3/12, MAGE-A10, MAGE-C1, MAGE-C2) and SSX2 are found to be broadly expressed in many tumor types." (PMID 38509571, 2024). "Further, we identify expression of SSX2 in circulating tumor cells (CTC) from patients with advanced PC." (PMID 27769045, 2016). "We demonstrate proof-in-concept data identifying expression of SSX2 in EpCAM positive circulating tumor cells from patients with advanced PC." (PMID 27769045, 2016). "The SYT gene (Chr 18) fuses with SSX1 (Chr X) to form biphasic tumour while fusion with SSX2 leads to monophasic tumour." (PMID 27446625, 2016). "Studies on the MYF5-CRE SS18/SSX2 transgenic model of SS found that SS18-SSX2 aberrantly activates Wnt/β-catenin signaling and that genetic deletion of β-catenin blocks tumor formation." (PMID 26905812, 2016). "Mice injected with the SSX2 knockdown line were found to have significantly increased lung weights and more tumor nodules." (PMID 27276714, 2016). "The tumor-specific pattern of expression of SSX2, along with the potent and selective activity of TCR-5, makes this TCR an attractive candidate for potential TCR gene therapy to treat multiple cancer histologies." (PMID 24681846, 2014). "Most tumours (32; 89%) were positive for SSX2-4 and amongst these, 14 (39%) were positive for SAGE1." (PMID 21706474, 2011). "The presence of SSX2 expression in so many tumor types suggested that this antigen is upregulated in cancer independently from fusion events with SS18, perhaps by alterations in methylation status or by the overexpression of SSX2 transcriptional activators." (PMID 20981248, 2010). "Fusion of SYT to SSX1, SSX2 and SSX4 causes inappropriate transcription of SSX sequences in synovial sarcoma that is characteristic of this tumour group." (PMID 12592363, 2003). "In conclusion, SSX2 may be expressed in PC both in situ in tumor tissue and in circulating tumor cells." (PMID 27769045, 2016). "SSX2 mRNA was only detected in 1 out of 9 patients' tumor tissue cultures at baseline (top row)." (PMID 27769045, 2016). "However, epigenetic treatments induced expression of SSX2 mRNA in all primary tumor tissue cultures." (PMID 27769045, 2016). "While some CTAs are especially prevalent in advanced or metastatic disease such as SSX2, significant heterogeneity in the expression profile of CTAs has been observed between different cancers including PC, tumor loci within the same host, or even within the same lesion." (PMID 27769045, 2016). "This expression pattern in metastases and in circulating tumor cells su­­ggests SSX2 could be functioning, or at least is expressed, in tumor cells with the capacity to disseminate." (PMID 27276714, 2016). "A decrease in focal adhesion could imply that factors leading to SSX2 expression aid in the extravasation from the primary tumor site into the blood stream and/or persistence of tumor cells in circulation." (PMID 27276714, 2016). "Due to the tumor-selective pattern of expression of SSX2, and the potent yet selective antigen-recognition properties of TCR-5, we decided to produce and test clinical-grade retroviral vectors suitable for the expression of TCR-5 in peripheral blood T cells of cancer patients." (PMID 24681846, 2014). "This expression prompted the investigators in the current study to evaluate whether SSX2 p19–34 is processed endogenously and presented on the surface of tumor cells." (PMID 20981248, 2010).
tumor (continued). "Not only has the endogenous processing and presentation of SSX2 peptide p103–111 been demonstrated by reactivity of p103–111-specific CTL for SSX2-expressing tumor cells, it has also recently been shown that this peptide epitope is directly presented on the surface of cancer cells." (PMID 20981248, 2010). "SSX2-, MoA-, and cross-reacting T cells were detected in the unstimulated PBMC of T-004 tumor patients." (PMID 38509571, 2024). "Intriguingly, these tumor-specific gene fusion events contain one TF of SSX2 and seven oncogenes of SS18, SSX1, SSX2, BCOR, CNOT1, HIST2H2AC, and TOP1." (PMID 36118864, 2022). "In this study we have shown SSX2 is the primary member of the SSX family expressed in prostate cancer, expressed in metastases and in circulating tumor cells." (PMID 27276714, 2016). "Furthermore, SSX2 was specifically enriched in the CD45−/EpCAM+/CD63+ subpopulation, which marks prostate-specific circulating tumor cells while differentiating from erythroid progenitor CD45−/EpCAM+ cells." (PMID 27276714, 2016). "All the tumours identified with FGFR3 or HRAS mutations expressed SSX2-4 (7/7), whereas all OCT2-positive tumours were mutation-negative (4/4); however, these differences were not statistically significant." (PMID 21706474, 2011). "In the case of both genes, it was observed that the last 78 C-terminal amino acids of SSX1 and SSX2 replaced the last 8 amino acids of the C-terminus of SS18 in most tumors, however, alternate fusions were also observed less frequently for some tumor specimens." (PMID 20981248, 2010). "For instance, a SS case that was previously shown to be negative for SYT/SSX1 and SYT/SSX2 gene expression by conventional RT-PCR, was instead found to be SYT/SSX4 positive, as the sole fusion transcript expressed in this tumor sample, when the RT-PCR was redesigned." (PMID 29751751, 2018).
cancer (30 papers, 2010 to 2025). A tumor composed of atypical neoplastic, often pleomorphic cells that invade other tissues. "NY-ESO-1, MAGEA4, PRAME, and SSX2 are potential cancer–testis antigens that have been associated with HL in various studies and tested in clinical trials." (PMID 38934093, 2024). "SSX2 expression has been associated with advanced disease and worse prognosis and can induce humoral and cellular immune responses in cancer patients." (PMID 38596293, 2024). "The SSX family genes were selected for the following reasons: the SSX2 gene was chosen on the basis of its expression in CC tissues or cell lines and its association with other cancers." (PMID 37241221, 2023). "The male germ cell-associated protein SSX2 is ectopically expressed in many types of cancer and is functionally involved in regulating chromatin structure and supporting cell proliferation." (PMID 31695025, 2019). "We describe herein a role for the germline- and cancer-associated protein SSX2 in modulation of PcG protein function." (PMID 25249625, 2014). "Here we present evidence that the germline- and cancer-associated protein SSX2 interacts with PcG bodies leading to their disintegration and derepression of PcG target genes." (PMID 25249625, 2014). "SSX2 expression was significantly higher in CC tissue samples with high disease grades than in NC tissue samples, suggesting that its expression is associated with cancer growth and metastasis." (PMID 37241221, 2023). "An important implication of our results is that reduced levels of MED1, MED4, or MED14 may support specific cancer-associated alterations (e.g., SSX2 expression)." (PMID 31695025, 2019). "Younger patient tumors were only enriched for 3 (5%) of these genes including one cancer testis antigen gene (SSX2) and two genes involved in T-cell recognition and killing of cancer cells (PVR, CXCR2)." (PMID 38975340, 2024). "This confirms previous research results, demonstrating increased SSX1 and SSX2 expression levels in numerous cancers, including CC." (PMID 37241221, 2023). "We co-cultured tumor associated antigen (TAAs: SSX2, PRAME, MAGEA4, SURVIVIN, and NY-ESO-1) specific CD8+ T cells with partially HLA-matched cancer cells expressing SURVIVIN, MAGE-A3, and MAGE-A4." (PMID 35681750, 2022). "Both PASD1 and SSX2 are CTAs that are expressed in cancer cells and immunologically protected sites." (PMID 29423088, 2018). "The SSX2 gene expression was appeared significantly up-regulated in the process of self-biosynthesized fluorescence Eu complex in cancer cells." (PMID 29069770, 2017). "The role of SSX2 in spermatogenesis and cancer development has remained elusive, but we demonstrate that SSX2 regulates PcG activity." (PMID 25249625, 2014). "These CD8 T cells recognized an epitope spanning residues 41–49 of SSX2, in a HLA-A*0201-restricted fashion and were found to be selectively expanded in patients with SSX2-expressing cancers." (PMID 24681846, 2014). "Similar to NY-ESO-1, XAGE-1b and SSX-2,4 are cancer/testis antigens shared among cancers of the prostate, lung, breast and others." (PMID 21504557, 2011). "Observing that cancer patients can have preexisting SSX2 IgG-specific immune responses, other investigators sought to identify if cancer patients can have cell-mediated immune responses to SSX proteins." (PMID 20981248, 2010). "This expression across different cancer histologies makes SSX2 an attractive target that may allow for treatment of patients with different diagnoses using a single clinical grade reagent." (PMID 24681846, 2014). "The SSX2 protein can induce spontaneous immune responses in cancer patients." (PMID 24681846, 2014). "Previous studies of PcG proteins in cancer have focused on changes in PcG levels during cancer progression, but the results presented herein demonstrate a novel level of PcG functional perturbation in cancer through SSX2-mediated control of polycomb body formation." (PMID 25249625, 2014).
cancer (continued). "Although the function of these proteins remains unknown, SSX1/SSX2 overexpression has been known to regulate stem cell migration, suggesting significant role in metastasis in cancer tissue." (PMID 25401222, 2014). "Under the differentially expressed genes we identified several genes previously related to cancer including the up-regulated SSX1, SSX2, RXFP2, RYR2 and the down-regulated CSTA, TSPAN7, NEO1, S100A, SERPINB5 and SEPP1." (PMID 25857299, 2015). "Examination of AML patients treated with azacitidine (AZA) and vorinostat (VOR) in a Phase II trial, demonstrated an increase in the expression of Cancer‐Testis Antigens (MAGE, RAGE, LAGE, SSX2 and TRAG3) on blasts and that these can be recognised by circulating antigen‐specific T cells." (PMID 30485425, 2019). "SSX2, another CTA, is a chromatin regulator and it has been inferred that it may regulate cancer cell proliferation through transcriptional regulation." (PMID 28446200, 2017). "SSX2 and GAGE1 genes were expressed in different types of cancer cells." (PMID 27454254, 2016). "Some of the investigated CT antigens have known oncogenic effects (e.g. MAGE-A, MAGE-C2, SSX2, PRAME), whereas the functions in cancer of some CT antigens such as NY-ESO-1 remain unknown." (PMID 26158218, 2015). "Indeed, SSX2 and MAGE-C1 are overexpressed in various cancers." (PMID 38509571, 2024). "More importantly, the significance of the up-regulation of SSX2 genes suggested fluorescent Eu complex could only be biosynthesized in cancer cells, without in normal cells." (PMID 29069770, 2017). "Therefore, SSX2, UBL4B and GAGE1 were further validated in 33 human cancer cell lines and tissues." (PMID 27454254, 2016).
SSX2 also shares sentences with these, for which no sentence is quoted: colon cancer (4 papers); glioma (3); acute myeloid leukemia (2); oligoastrocytoma (2); pancreatic cancer (2); soft tissue tumor (2); undifferentiated sarcoma (2); angiomatoid fibrous histiocytoma (1); astrocytomas (1); chronic myelogenous leukemia (1); clear cell sarcoma (1); colorectal carcinoma (1); epithelial ovarian cancer (1); Ewing sarcoma (1); gynecological cancers (1); head and neck cancer (1); Hodgkins lymphoma (1); infantile fibrosarcoma (1); intrahepatic cholangiocarcinoma (1); liposarcoma (1); lung carcinoma (1); lymphoma (1); mesothelioma (1); myopathy (1); myxoid liposarcoma (1); neuroblastoma (1); osteosarcoma (1); ovarian cancer (1); salivary duct carcinoma (1); small cell sarcoma (1).
A further 8 diseases each share a sentence with SSX2 in 1 paper.